SIGLEC9 (sialic acid binding Ig like lectin 9)
Description:
Putative adhesion molecule that mediates sialic-acid dependent binding to cells. Preferentially binds to alpha-2,3- or alpha-2,6-linked sialic acid. The sialic acid recognition site may be masked by cis interactions with sialic acids on the same cell surface.
Synonyms: Siglec-9; CD329; CDw329; FOAP-9; OBBP-LIKE
Tractability: Antibody: its Gene Ontology location is reachable by antibodies, with high confidence; UniProt predicts a signal peptide or a membrane-spanning region. PROTAC: its protein half-life has been measured; a small molecule that binds it is known.
Target class: Adhesion
Gene: Protein-coding gene on chromosome 19 (51,124,906 to 51,140,470, forward strand). Ensembl gene ENSG00000129450.
Subcellular location: Membrane
Pathways (Reactome):
Immune System: Immunoregulatory interactions between a Lymphoid and a non-Lymphoid cell; Neutrophil degranulation
Gene Ontology:
Molecular function: protein binding; carbohydrate binding; sialic acid binding
Biological process: cell adhesion; cell surface receptor signaling pathway
Cellular component: plasma membrane; secretory granule membrane; membrane
Genetic constraint (gnomAD): Loss-of-function variants: 26 observed, 41.79 expected, observed/expected ratio (o/e) 0.62, 90% interval 0.46 to 0.86. The upper end of that interval is the gene's LOEUF score, 0.86, which puts it in group 3 of 6, group 1 being the genes least tolerant of losing a copy. Missense variants: 556 observed, 609.78 expected, observed/expected ratio (o/e) 0.91, 90% interval 0.85 to 0.98. Synonymous variants: 236 observed, 259.45 expected, observed/expected ratio (o/e) 0.91, 90% interval 0.82 to 1.01.
Homologues: Orthologues: chimpanzee SIGLEC9 (87% identical), macaque SIGLEC9 (86% identical), rat Siglec8 (54% identical), mouse Siglece (52% identical), tropical clawed frog siglecl2 (26% identical), tropical clawed frog siglecl2 (25% identical), tropical clawed frog siglecl1 (24% identical), tropical clawed frog siglecl1 (18% identical). Paralogues in human: SIGLEC7 (77% identical), SIGLEC12 (71% identical), SIGLEC8 (71% identical), SIGLEC6 (49% identical), SIGLEC5 (47% identical), SIGLEC10 (42% identical), CD33 (42% identical), SIGLEC11 (41% identical), SIGLEC14 (41% identical), SIGLEC1 (24% identical), MAG (23% identical), SIGLEC16 (19% identical), and 4 more.
Diseases named in the same sentence as SIGLEC9 in open-access papers:
SIGLEC9 is named in the same sentence as 53 diseases in open-access papers, as found by Europe PMC text mining. Sharing a sentence is not in itself a finding about the gene and the disease. The quoted sentences say what the papers report.
glioma (5 papers, 2022 to 2024). A benign or malignant brain and spinal cord tumor that arises from glial cells (astrocytes, oligodendrocytes, ependymal cells). "The Cancer Genome Atlas (TCGA) and the Chinese Glioma Genome Atlas (CGGA) databases were used to analyze the association of SIGLEC9 expression levels with tumor stages and survival probability." (PMID 35756603, 2022). "The results of the TCGA database showed that SIGLEC9 expression was higher in IDH wild-type glioma patients than in IDH mutated glioma patients." (PMID 35756603, 2022). "Furthermore, we investigated the underlying functions of SIGLEC9 in glioma pathogenesis, and we found that SIGLEC9 might regulate the TME to induce tumor growth, metastasis, and the therapy resistance of gliomas." (PMID 35756603, 2022). "MSI status has been negatively associated with SIGLEC9 expression in head–neck squamous cell carcinoma (HNSC), glioma, lung cancer, pancreatic adenocarcinoma (PAAD), SKCM, and tenosynovial giant cell tumors (TGCTs), but positively in CRC." (PMID 39727942, 2024). "This is partly in line with the previous findings that SIGLEC9 is mainly expressed on macrophages in lung cancer sections and glioma." (PMID 36688997, 2023). "In patients with glioma, high SIGLEC9 expression was detected in high-grade tumors, which was positively linked to the M2 skewing of TAMs." (PMID 36688997, 2023). "Our results revealed that tumor-related immune cells, such as MDSCs, regulatory T cells, and neutrophils, were positively correlated with SIGLEC9 expression in gliomas." (PMID 35756603, 2022). "Then, we investigated the protein levels of SIGLEC9 in 177 glioma patients from Sanbo Brain Hospital Capital Medical University." (PMID 35756603, 2022). "In this study, we assessed the correlation between the clinical characteristics and SIGLEC9 expression in glioma patients." (PMID 35756603, 2022). "In this study, we investigated the correlation between the immune microenvironment and the SIGLEC9 levels in gliomas." (PMID 35756603, 2022). "In the CGGA database, the expression of SIGLEC9 in grade IV glioma patients was higher than in grade II patients." (PMID 35756603, 2022). "Firstly, we analyzed the correlation between immune cell infiltration and SIGLEC9 expression in gliomas with TCGA database." (PMID 35756603, 2022). "Gene Set Enrichment Analysis (GSEA) was conducted to reveal the biological functions of SIGLEC9 in gliomas." (PMID 35756603, 2022). "We investigated the SIGLEC9 expression in different grades and subtypes of glioma patients with TCGA and CGGA databases." (PMID 35756603, 2022). "Glioma patients with high SIGLEC9 expression have significantly enhanced infiltration of immune cells, such as T cells, NK cells, neutrophils, aDC, B cells, DC cells, iDC cells, macrophages, mast cells, Th1, Th2, Th17, and so on." (PMID 35756603, 2022). "In this study, we comprehensively analyzed the expression pattern of SIGLEC9 in gliomas with TCGA and CGGA databases." (PMID 35756603, 2022). "This study aimed to investigate the diagnostic value and underlying mechanisms of sialic acid-binding Ig-like lectin 9 (SIGLEC9) in gliomas." (PMID 35756603, 2022). "The expression patterns of SIGLEC9 in different grades and subtypes of glioma patients from the CGGA database were similar to that of TCGA database." (PMID 35756603, 2022). "As for the four subtypes, including classic, mesenchymal, and proneural subtypes, SIGLEC9 expression was higher in the mesenchymal subtype than in the other two subtypes of gliomas in TCGA database." (PMID 35756603, 2022). "Thus, SIGLEC9 was considered to exacerbate the gliomas by suppressing the anti-tumor immune response." (PMID 35756603, 2022). "Then, we investigated the underlying mechanisms of SIGLEC9 in gliomas, and our results showed that SIGLEC9 might regulate the tumor microenvironment (TME) in gliomas." (PMID 35756603, 2022). "Finally, we calculated the expression of SIGLEC9 in these cell subsets between glioma tissue and adjacent tissue." (PMID 35756603, 2022).
glioma (continued). "In summary, SIGLEC9 might regulate the TME in gliomas to exacerbate the disease, and MDSCs and neutrophils play an important role in the function of SIGLEC9." (PMID 35756603, 2022). "Furthermore, related mechanisms were discovered about SIGLEC9 in glioma tumorigenesis, and we reveal how SIGLEC9 functions in macrophages through single-cell analysis." (PMID 35756603, 2022). "In this study, we analyzed the expression patterns and prognostic values of SIGLEC9 in glioma." (PMID 35756603, 2022). "Macrophages play an essential role in glioma, and SIGLEC9 may be an important regulator of macrophages." (PMID 35756603, 2022). "Lastly, functional enrichment analysis was performed to discover the role of SIGLEC9 in gliomas." (PMID 35756603, 2022). "Moreover, GSEA was conducted to explore the biological functions of SIGLEC9 in gliomas." (PMID 35756603, 2022). "Therefore, we will reveal the effect of SIGLEC9 as an immune checkpoint on the immune microenvironment of glioma and provide a theoretical basis for the further development of immunotherapeutic agents for glioma." (PMID 35756603, 2022). "Moreover, SIGLEC9 might upregulate the expression of immune checkpoint genes to suppress the anti-tumor immune response in gliomas." (PMID 35756603, 2022). "SIGLEC9 expression was significantly upregulated in malignant pathological types, such as grade III, grade IV, mesenchymal subtype, and IDH wild-type gliomas in TCGA and CGGA database." (PMID 35756603, 2022). "The expression of SIGLEC9 in grade III and grade IV glioma patients was higher than in grade II glioma patients." (PMID 35756603, 2022). "In addition, SIGLEC9 expression was significantly upregulated in malignant pathological types such as grade III, grade IV, mesenchymal subtype, and IDH wild-type gliomas." (PMID 35756603, 2022). "SIGLEC9 was upregulated significantly in malignant pathological types, such as grade III, grade IV, mesenchymal subtype, and isocitrate dehydrogenase wild-type gliomas." (PMID 35756603, 2022). "In addition, high SIGLEC9 expression presented to have a shorter survival probability in patients with age ≧60 years, with grade IV glioma, with GBM, with ATRX loss glioma, without radiotherapy, or without chemotherapy." (PMID 35756603, 2022).
melanoma (5 papers, 2023 to 2025). A malignant, usually aggressive tumor composed of atypical, neoplastic melanocytes. "We successfully discovered Desmoglein 2 (DSG2) as a functionally important counter receptor for Siglec‐9 in human melanoma cell line A375." (PMID 39813162, 2025). "Here, proximity labeling combined with genetic screening to identify DSG2 as a dominant counter receptor of Siglec‐9 in melanoma." (PMID 39813162, 2025). "Blocking trans interaction between DSG2 and Siglec‐9 significantly enhances macrophage phagocytosis of melanoma cells, presenting sialylated DSG2 as a potential target in cancer immunotherapy." (PMID 39813162, 2025). "Here, the identification of DSG2 (Desmoglein 2) as a dominant counter receptor of Siglec‐9 in melanoma cells is reported, using a workflow that combines the strength of proximity labeling and the advantage of CRISPR knockout screening." (PMID 39813162, 2025). "Most of the tumor-infiltrating CD8+ T cells in melanoma specimens express SIGLEC9, which binds to the ligands on the surface of tumor cells, thus inhibiting T-cell response in the tumor microenvironment." (PMID 37207210, 2023). "We found that most of the cells which expressed SIGLEC9 in melanoma were clustered together, but the more scattered expression was found in normal tissues." (PMID 37207210, 2023). "We analyzed the expression of SIGLEC9 in the melanoma microarray cohort, which contained 38 primary tumors, 10 metastatic tumors, and 15 normal tissues." (PMID 37207210, 2023). "We have also demonstrated that the trans interaction between DSG2 on A375 melanoma cells and Siglec‐9 on macrophages has a significant impact on the Siglec‐9‐mediated immunosuppressive signaling and knocking down DSG2 releases immunosuppression and increases phagocytosis." (PMID 39813162, 2025). "Importantly, blocking trans interaction between DSG2 and Siglec‐9 significantly enhances macrophage phagocytosis of melanoma cells and, to a lesser extent, other cancer cells." (PMID 39813162, 2025). "To test this hypothesis, we first confirmed that blocking Siglec‐9 signaling does enhance the phagocytosis of melanoma cells." (PMID 39813162, 2025). "Importantly, expression of Siglec‐9 has previously been found on tumor infiltrating T cells in non‐small cell lung cancer and melanoma." (PMID 39246414, 2024). "SIGLEC9 overexpression on T cells reduced the secretion of INFy and TNFa against melanoma." (PMID 39727942, 2024). "In addition, hyper-sialylation of melanoma suppresses effector functions of tumor-infiltrating Siglec9+ T cells." (PMID 36891308, 2023). "Given the specific interaction of DSG2 with Siglec‐9 in A375 cells, the function of DSG2 in melanoma could be related to Siglec‐9 and its immunosuppressive signaling in immune cells." (PMID 39813162, 2025).
breast carcinoma (4 papers, 2020 to 2024). "We assessed Siglec‐7 and Siglec‐9 (ligand) expression in TN and ER+ breast cancer tumors and their breast cancer cell line‐induced signalling." (PMID 39246414, 2024). "Here we report on the expression of Siglec‐7 and Siglec‐9 and their ligands in TN and ER+ tumors and on Siglec‐7 and Siglec‐9 signalling induced by breast cancer cells to determine their potential as targets for future immunotherapy in breast cancer." (PMID 39246414, 2024). "Analysis of Siglec‐7 and Siglec‐9 expression and function in TN and ER positive breast cancer showed that TN tumors express higher Siglec‐7 and Siglec‐9 RNA and protein levels as compared to ER+ tumors." (PMID 39246414, 2024). "In this study, we found high Siglec‐7 and Siglec‐9 (ligand) expression in triple negative breast cancer, and to a lower extent in oestrogen receptor positive breast cancer." (PMID 39246414, 2024). "We therefore hypothesise that Siglec‐7 and Siglec‐9 might be signalling to induce immune cell inhibition in breast cancer." (PMID 39246414, 2024). "Moreover, BASEscope analysis of our cohort of breast cancer showed expression of SIGLEC9 within the stroma, edge and nest of the tumour in a similar manner to CD163 staining." (PMID 33149188, 2020). "Siglec‐7 expression in the breast cancer TME was found on T cells, myeloid cells and NK cells in human breast tumors, whereas Siglec‐9 was observed on myeloid cells." (PMID 39246414, 2024). "Analysis of the immune cells expressing Siglec‐7 and Siglec‐9 in the breast cancer TME revealed Siglec‐7 expression on CD3+ T cells, CD11b+ myeloid cells and CD56+ NK cells, and Siglec‐9 on CD11b+ cells." (PMID 39246414, 2024). "The influence of Siglec‐7 and Siglec‐9 signalling on TAM polarisation and MDSC function in breast cancer requires more extensive investigation." (PMID 39246414, 2024). "We therefore envision that immunotherapy targeting Siglec‐7 and/or Siglec‐9 is particularly promising for TN breast cancer patients who do not respond to current treatment options with tumors presenting with high immune cell infiltration." (PMID 39246414, 2024). "Analysis of the TCGA breast cancer database shows a highly significant correlation between CD163 or CD68 and SIGLEC9 but not with the epithelial markers, EPCAM or KRT8." (PMID 33149188, 2020).
colorectal cancer (4 papers, 2020 to 2025). A primary or metastatic malignant neoplasm that affects the colon or rectum. "SIGLEC9-expressing T cells in patients with non-small cell lung cancer correlate with diminished survival, whereas SIGLEC9 polymorphisms are associated with the risk of developing lung and colorectal cancer." (PMID 37133224, 2023). "High infiltration of SIGLEC9+ TAMs has been associated with poor prognosis, and these cells may serve as biomarkers for prognosis assessment in colorectal cancer patients." (PMID 41418390, 2025). "SIGLEC9 (sialic acid-binding Ig-like lectin 9) is a molecule thought to have a significant influence on the immune properties of the colorectal cancer (CRC) tumor microenvironment (TME)." (PMID 39727942, 2024). "The increased expression of the SIGLEC9 protein in high-grade colorectal cancer tumors appears to shed new light on the potential prognostic significance of this molecule in CRC." (PMID 39727942, 2024). "A thorough understanding of the impact of targeting SIGLEC9 expression on the immunological properties of tumors, as well as potential clinical outcomes, warrants further investigation into the significance of SIGLEC9 in colorectal cancer." (PMID 39727942, 2024). "The expression of SIGLEC9 was significantly elevated in colorectal cancer tissues, independent of mutations in the KRAS, NRAS, BRAF, PIK3CA, and AKT genes, as well as MSI status." (PMID 39727942, 2024). "SIGLEC9 upregulation was observed in tumor-infiltrating lymphocytes (TILs), including CD4+ and CD8+ T cells in colorectal cancer (CRC)." (PMID 39727942, 2024).
lung cancer (4 papers, 2023 to 2024). A malignant neoplasm involving the lung. "SIGLEC9 upregulation was related to poorer overall survival (OS) and 5-year OS in lung cancer, esophageal carcinoma, and low-grade gliomas (LGGs), while the opposite results were obtained for adenoid cystic carcinoma (ACC)." (PMID 39727942, 2024).
amyotrophic lateral sclerosis (3 papers, 2023 to 2025). Amyotrophic lateral sclerosis (ALS) is a neurodegenerative disease characterized by progressive muscular paralysis reflecting degeneration of motor neurons in the primary motor cortex, corticospinal tracts, brainstem and spinal cord. "In our AD EA TWAS, we also identified genes associated with other neurological and autoimmune diseases, including Parkinson’s disease (CYB561 and SLC25A39), Crohn’s disease (ATG16L1), Amyotrophic lateral sclerosis (SIGLEC9), and Riboflavin Transport Deficiency (SLC52A1)." (PMID 40141087, 2025). "Mendelian randomization analyses suggested causal roles for several proteins, for example, ApoE, CD33, and GRN in Alzheimer's disease, MMP‐10 in preclinical Alzheimer's disease, SIGLEC9 in amyotrophic lateral sclerosis, and CD38, GPNMB, and ADAM15 in Parkinson's disease." (PMID 36504281, 2023).
breast tumor (2 papers, 2023 to 2024). "Immunohistochemical stainings for Siglec‐7 and Siglec‐9 of nine TN breast tumors and eight ER+ breast tumors were performed." (PMID 39246414, 2024). "Indeed, hyper-sialylated MUC1 on breast tumor cells drove myeloid cells towards immunosuppressive TAMs through engagement of SIGLEC9, leading to tolerance." (PMID 36891308, 2023).